STAT3 (signal transducer and activator of transcription 3)
Diseases named in the same sentence as STAT3 in open-access papers (continued):
Sharing a sentence is not in itself a finding about the gene and the disease.
tumor (continued). "It was concluded that the tumor biological effects of IL-6/STAT3 signaling were similar between the PDAC subtypes, but differed strongly between the sexes, especially with regard to T cell populations." (PMID 39684385, 2024). "A subset of reactive astrocytes exhibits a signal transducer and activator of transcription 3 (STAT3) activity induced by tumor cells, which modulates immune responses, ultimately converting the naive “soil” into a tumor-promoting environment." (PMID 38231464, 2024). "To further evaluate the effect of STAT3 in vivo, we established a subcutaneous tumor xenograft model." (PMID 39000312, 2024). "Fluacrypyrim (FAPM) is a recognized effective inhibitor of STAT3, which exhibits anti-inflammation and anti-tumor effects in hematopoietic disorders." (PMID 38398568, 2024). "Astragaloside IV inhibits the secretion of IL-10 from tumor cells by downregulating the expression of STAT3 and NF-κB in tumor cells." (PMID 39085255, 2024). "This compound has gained attention for its ability to inhibit cancer stemness by targeting the STAT3 pathway, which plays a crucial role in tumor growth, survival, and the regulation of inflammation within the tumor microenvironment." (PMID 38673727, 2024). "Overexpression of TGFβ and IL10R2 enhances IL22/STAT3 signaling in colitis-associated colorectal carcinogenesis, and Wnt5a-mediated IL10 secretion from macrophages ultimately promotes tumor growth and metastasis." (PMID 38844562, 2024). "Comparing non-sarcomatoid to sarcomatoid samples, bivariate Moran’s I did not identify any ligand-receptor pairs from either EMT or IL6/JAK/STAT3 gene sets that were spatially correlated in either the tumor or stroma FOV." (PMID 39639369, 2024). "Immunohistochemical staining of tumors at the end of the study showed a dramatic reduction in STAT3 levels in tumor samples treated with BP1003 alone." (PMID 39200368, 2024). "In a particular study, the suppression of MUC2, the primary component of intestinal mucus, resulted in the phosphorylation of STAT3 in tumor cells via the cytokine IL-6." (PMID 38709264, 2024). "This alteration activated the intestinal AHR and GPCRs signaling pathways while inhibiting STAT3 phosphorylation, which subsequently suppressed tumor cell proliferation and angiogenesis." (PMID 39710789, 2024). "The interaction of M2-TAM and via STAT3/NF-κB with the tumor cells in TME creates a hostile environment for the immune cells but a favorable one for tumor progression." (PMID 39061137, 2024). "The CXCL12/CXCR4/ACKR3 signaling axis activates the STAT3 pathway, playing a central role in tumor proliferation, metastasis, anti-apoptosis, maintenance of tumor stemness, and immune escape." (PMID 38920657, 2024). "Therapeutically, gp130 blocker SC144 was added to investigate the contribution of IL-6/STAT3 signaling to tumor progression in subcutaneous LLC and BMDM co-implantation models in vivo." (PMID 38274367, 2024). "Previous studies have shown that IL-17 contributes to the occurrence of tumors by affecting the activation status of the STAT3 signaling pathway in tumor cells." (PMID 38740736, 2024). "When translocated, PKM2 interacts with Wnt signaling to regulate the activity of OCT4 and STAT3 transcription factors, ultimately impacting tumor cell proliferation." (PMID 39061173, 2024). "In these ways, STAT3 shapes the metabolism to provide more favorable energy and metabolic intermediates for rapid tumor growth in the conditions of metabolic stress." (PMID 38245798, 2024). "This feed-forward loop also allows for the perpetual activation of STAT3 and continuous expression of these pro-tumor genes." (PMID 38464736, 2024). "Recent researches indicate that the STAT3/TC45 pathway in various tumor biological functions such as proliferation, metastasis, and radio-resistance." (PMID 39198402, 2024). "STAT3 is an important transcription factor involved in both tumor growth and maintenance the stemness of cancer cell, as well as embryonic stem cells." (PMID 38977663, 2024).
tumor (continued). "Approximately 60 % of phosphorylated STAT3 can be detected in human HCC tissues and sustained activation of STAT3 leads to the self-renewal of tumor stem cells and tumor susceptibility to recurrence, metastasis and progression." (PMID 38699038, 2024). "The aberrant activation of STAT3 supports and promotes tumor growth and development through a multitude of processes, which include the promotion of cell proliferation, angiogenesis, metastasis, immune suppression, and stemness." (PMID 38464736, 2024). "The transcription factor signal transducer and activator of transcription factor 3 (STAT3) plays a fundamental role in mediating the tumor-promoting effect of IL-6, and the IL-6/STAT3 trans-signaling pathway is a key regulator of tumor differentiation." (PMID 39911672, 2024). "Inhibition of the STAT3 pathway has the potential to prevent tumor progression, treat residual disease and promote anti-tumor immunity." (PMID 39272915, 2024). "In PDAC tumor tissues from human patients, sorcin was highly expressed in the cytoplasm of PC cells, while p-STAT3, an activated transcription factor, was enriched in the nucleus." (PMID 39516378, 2024). "IL-6 secreted by senescent tumor cells acted on TAMs, up-regulated TAMs CD73 expression through JAK/STAT3 signaling pathway, and suppressed anti-tumor immunity." (PMID 38323313, 2024). "TANs 2 also regulate tumor growth via the IL-6/STAT3 axis and proangiogenic as well as metastatic markers, such as VEGF and MMP9." (PMID 39335210, 2024). "Reciprocally, tumor cells induced STAT3 signaling to up-regulate FGF7 expression at the transcript level in CAFs." (PMID 39594574, 2024). "Future studies are warranted to gain more mechanistic insights on STAT3 stability in ascites and tumour microenvironment." (PMID 38939897, 2024). "The reprogramming of TME such as hypoxia, inflammatory cytokines, abnormal pH, or altered crosstalk between tumor cells and microenvironment as disease progresses also accelerates a secondary STAT3 activation following primary therapy." (PMID 38245798, 2024). "In the TME, IL-6 can bind its receptor, transmit signals through the downstream JAK/STAT3 pathway, and activate the transcription of tumor-related genes." (PMID 39372416, 2024). "Meanwhile, our research has unveiled the targeting agent EGR3 of C6 ceramide, which functions as a tumor suppressor gene by regulating the JAK1/STAT3 signaling pathway." (PMID 38338065, 2024). "A variety of ALK inhibitors are available, including crizotinib, ceritinib, lorlatinib, alectinib, entrectinib and brigatinib, that can downregulate the STAT3 pathway in patients with ALK-positive pcALCL, thereby causing apoptosis among tumour cells." (PMID 38337516, 2024). "Meanwhile, it also provides us with new research ideas: Can STAT3 regulate the differentiation of other tumor-related immune cells?" (PMID 38172648, 2024). "Our research extends the understanding of p27 tumour suppressive function by revealing its inhibitory effect on the JAK1/STAT3 pathway." (PMID 39099000, 2024). "IL-10 exhibited carcinogenic function by activating the STAT3 pathway and inducing Tregs production and exerted anti-tumor effects by downregulating angiogenic factors." (PMID 38918817, 2024). "IL-6/STAT3 signaling plays a crucial role in modulating tumor-infiltrating immune cells within the tumor microenvironment." (PMID 39830506, 2024). "In a mouse model, tumor cells also induce mTOR expression in microglia, and mTOR-mediated STAT3 signaling contributes to the M2-like microglial phenotype, which impairs effector T cell infiltration, tumor proliferation, and immune responses." (PMID 39194524, 2024). "It has been observed that CAFs can directly secrete IL-6, and IL-8 stimulates STAT3/Notch signaling pathways to sustain the stemness of tumor cells." (PMID 39578849, 2024).
tumor (continued). "For that, we studied the interaction of tumor associated macrophages (TAM) and STAT3 and NFkB pathways with of several cancer hallmarks in 691 patients with CC, and more importantly, their impact on clinical outcome of these patients." (PMID 39061137, 2024). "In the orthotopic mouse model, p-FAK, p-STAT3 and IL-4 were significantly decreased in tumor tissues of Postn-/-Rag1-/- mice compared to Postn+/+Rag1-/- mice." (PMID 38773979, 2024). "A single-cell transcriptomic study of oral squamous cell carcinoma has revealed an enrichment of the IL-6/JAK2/STAT3 axis in the tumor microenvironment, particularly in cell populations like macrophages, in samples induced by chemotherapy and other treatments." (PMID 38650924, 2024). "In this regard, it has been shown recently that the SIN3A transcriptional repressor complex interacts with STAT3 and is involved in silencing tumor repressor genes, thus promoting cell survival in different cancers." (PMID 38168833, 2024). "Another study showed that tumor cells were able to induce stromal cells, including MSCs, to produce miR-214-rich EVs upon the activation of IL-6/STAT3 signaling, which favored the tumor dissemination." (PMID 39161894, 2024). "The upregulation of c-Myc activity, facilitated by the IFN-γ-STAT3 signaling axis, underscores the pivotal role of transcription factors in integrating signaling cues from the tumor microenvironment with cellular metabolism and growth." (PMID 38791327, 2024). "Remarkably, elevated acetylation levels of STAT3 within tumor tissues can bind to DNMT1, resulting in the inhibition of tumor suppressor genes via promoter CpG island methylation." (PMID 38834851, 2024). "Among the small molecules, BP-1-102 and its two analogs were designed as direct STAT3 inhibitors with reasonable in vivo tumor-inhibiting activity by binding specifically to the STAT3 SH2 domain." (PMID 38611065, 2024). "For example, FTO is involved in the degradation of miR-1266 or reducing expression levels of STAT3, cyclin D, and MMPs to stimulate tumor growth." (PMID 39136000, 2024). "We also observe abnormal overexpression and activation of the cytoplasmic transcription factor STAT3 during tumor progression." (PMID 39409068, 2024). "In tumor tissues, there was a moderate correlation between IL-6 and STAT3 (r = 0.449, P < 0.001), whereas a weak correction between IL-6 and gp130 (r= 0.314, P = 0.002), as well as JAK2 (r = 0.230, P = 0.028)." (PMID 38881895, 2024). "On the other hand, STAT3 is an oncogenic transcription factor known to play a role in various biological functions during human tumor development, including proliferation, survival, and inflammation." (PMID 38388902, 2024). "In animal models of NSCLC, including patient-derived xenograft (PDX) tumor xenografts, W2014-S inhibited cancer growth, demonstrating proof of concept in preclinical studies of STAT3 driven NSCLC tumors." (PMID 38464736, 2024). "Initially, microglia adopt an anti-tumor M1 phenotype but gradually transition to a pro-tumor M2 phenotype under the influence of tumor-derived cytokines, specifically STAT3." (PMID 38396722, 2024). "Overall, this study demonstrated that miR-4458 increases anti-tumor immunity in NSCLC by targeting STAT3 to downregulate PD-L1 expression." (PMID 39343796, 2024). "IL6 can impact on neighbouring tumour cells via the IL6 cytokine receptor, causing activation of JAK and STAT3 signalling leading to changes in gene expression and cellular proliferation." (PMID 38535967, 2024). "The JAK2/STAT3 signaling pathway plays an important role in increasing tumor metastatic ability and chemoresistance in cancer by promoting epithelial – mesenchymal transition (EMT)." (PMID 39588922, 2024). "STAT3 degraders that promote the ubiquitination of STAT3 have been found to inhibit the growth of cancer cell lines and achieve tumor regression." (PMID 39195486, 2024).
tumor (continued). "Dysregulation of the major signaling cascades, such as MAPK, PI3K/PTEN/AKT, JAK/STAT3, Notch, and NF-KB, promotes malignant tumor phenotypes (chemoresistant, metastatic, and proliferative), ultimately leading to poor clinical outcomes." (PMID 38607050, 2024). "Tumor-derived factors such as VEGF, IL-6, and IL-10 recruit MDSCs which in turn produce more VEGF via STAT3 signaling, thereby establishing a positive feedback loop that potentiates tumor angiogenesis." (PMID 38520006, 2024). "This pattern was also observed in the tumor microenvironment, where there was a noticeable rise in T cells expressing NKp46, FasL, IL-17, and STAT3, along with a decrease in PD-1+ and FoxP3+ T cells." (PMID 38892058, 2024). "Clinical studies have shown that STAT3 is persistently activated in 22-65% of NSCLC patients, and STAT3 activity is correlated with tumor progression, poor prognosis, and short patient survival." (PMID 38424624, 2024). "Expanding the scope of potential therapeutic targets beyond STAT3 allows for the initiation of clinical trials investigating the efficacy of therapies on other critical transcription factors in cells of the PDAC tumor." (PMID 38464736, 2024). "In our current study, we gathered clinical samples of ATC, PTC, and NT tissues and established a noteworthy confirmation of the heightened expression levels of JAK1, p-JAK1, JAK2, p-JAK2, STAT3, and p-STAT3 proteins within the tumor cells of ATC patients." (PMID 38336839, 2024). "Studies have shown that vWF is an independent predictor of HCC occurrence and is associated with tumor mass, tumor growth, worsening of PHT, and metastatic dissemination acting on the STAT-3 pathway." (PMID 38611066, 2024). "Clinical studies have shown that STAT3 overexpression, occurring in 60% of HCC cases in vitro, is associated with worse disease prognosis, including larger tumor size, increased tissue vascularization, and higher migration potential." (PMID 39409068, 2024). "Our findings align with recent studies indicating the crucial role of the IL-6/JAK/STAT3 signaling axis in cancer progression, particularly in influencing the tumor immune microenvironment." (PMID 38429845, 2024). "IGFBP2 promotes tumor progression by inducing the alternative polarization of macrophages through the STAT3 pathway." (PMID 39335579, 2024). "IL-6 triggers the production of STAT3, a factor that promotes tumor growth in the process of carcinogenesis." (PMID 39834817, 2024). "TAM-derived IL-6 activated the JAK2/STAT3 pathway, and activated STAT3 inhibited transcription of the tumor suppressor miR-506-3p in CRC cells." (PMID 39199574, 2024). "Studies have also explored the regulatory relationship between STAT3 and microRNAs, which ultimately influences tumor oncogenesis." (PMID 38273295, 2024). "Nifuroxazide has been demonstrated to inhibit the expression of p-STAT3, thereby suppressing tumor cell proliferation and migration." (PMID 38441416, 2024). "The activation of SUCNR-1 also leads to upregulation of VEGF expression through the activation of ERK1/2 and STAT3, inducing tumor angiogenesis." (PMID 38185636, 2024). "Pyrimethamine (PYR), a STAT3 inhibitor, has been shown to reduce tumour burden in mouse cancer models." (PMID 38618181, 2024). "NR3C1, STAT1, and STAT3 showed higher expression levels in tumor tissues, and all of these transcription factors were shown to be associated with T cell depletion status and terminal T cells." (PMID 38604154, 2024). "The STAT3 signaling pathway has been extensively studied in tumor research due to its critical role in promoting tumorigenesis." (PMID 38246919, 2024). "IHC analysis demonstrated that p-STAT3 and Ki67 were decreased in tumor tissue, while c-caspase 3 was increased." (PMID 39169307, 2024). "Mechanistically, previous studies have reported that silibinin acts as an efficient inhibitor of heat shock protein 90 and signal transducer and activator of transcription 3 to inhibit tumor growth." (PMID 38222315, 2024).
tumor (continued). "A recent study revealed a mechanistic link between the lactylation and activation of STAT3 in tumor-infiltrating myeloid cells (TIMs)." (PMID 39516356, 2024). "In the present study, we demonstrated the contribution of GP73 to the amplification and transmission of GRP78-induced ERS signals for the activation of JAK2/STAT3 signals in the processing of tumor vasculature." (PMID 38939041, 2024). "As previously reported, IL-6 binds to receptors on the surface of tumour cells and activates gp130 to phosphorylate STAT3." (PMID 38504172, 2024). "We also demonstrated that HDAC6 inhibition in macrophages suppressed the polarization toward tumor-promoting phenotype by attenuating STAT3-mediated M2 reprogramming." (PMID 39272209, 2024). "In the recurrence of HCC, NUSAP1 can enhance tumor stemness by stimulating STAT3 nuclear translocation and RACK1 activation." (PMID 38441732, 2024). "Recent studies also indicate that inhibiting STAT3 can activate cell pyroptosis and elicit anti-tumor immune responses." (PMID 39069522, 2024). "STAT3 is well-known to be closely related with EMT in driving tumor aggressiveness, and was also identified as one of the master transcriptional regulators for MES GBM8,45." (PMID 38548861, 2024). "Inhibition of mTOR by the addition of rapamycin, upregulation of TSC2 or blockade of STAT3 in monocytes/macrophages has been shown to promote the release of M1 cytokines and inhibit tumor growth, which was confirmed by reduced tumor angiogenesis." (PMID 39003350, 2024). "Direct interactions of the protein with Janus kinase 2 (JAK2) and signal transducer and activator of transcription 3 (STAT-3) cause the phosphorylation of the latter and induce TNF-α and IL-1β secretion, which in turn facilitate tumour metastasis." (PMID 39273582, 2024). "Meanwhile, IL32β has been demonstrated to inhibit tumor growth by activating cytotoxic lymphocyte and inactivating NF-κB and STAT3 pathways through alterations in cytokine levels within the tumor tissue." (PMID 38648200, 2024). "Once in an immunosuppressive tumoral microenvironment (TME), macrophages take over an essential role by activating signaling pathways such as STAT3 and NFkB to keep the immune suppression and tumor progression." (PMID 39061137, 2024). "STAT3 confers tumor great malignancy by promoting tumor invasion, migration, metastasis and angiogenesis, which led to it being considered a critical therapeutic target." (PMID 39000312, 2024). "We further showed that both CpG-Stat3 siRNA and CTLA4 antibody inhibit STAT3 in B malignant cells, leading to tumor cell apoptosis and/or growth inhibition." (PMID 39618825, 2024). "Studies have shown that exosomes derived from TAMs transport miR-29a-3p and miR-21-5p to CD4+ T cells, leading to Treg/Th17 imbalance and inducing EOC tumour growth and metastasis by directly targeting STAT3." (PMID 38302430, 2024). "Wei’s research showed that the expression of CAV1 was significantly reduced in NSCLC, and overexpression of CAV1 can reduce cell migration by affecting the phosphorylation of STAT3, exerting a tumor suppressive effect." (PMID 39165641, 2024). "It mitigates colitis severity, inflammation, and tumor development by modulating TLR4-mediated NF-κB and STAT3 activation, suppressing tumor growth factors." (PMID 38930793, 2024). "Meanwhile, blocking STAT3 by inhibitor abolishes the tumor-suppressive function of exosome p120-catenin." (PMID 38245798, 2024). "A recent study indicates that in liver cancer induced by fibrosis, GP73 within tumor cells activates STAT3 phosphorylation, which in turn upregulates PD-L1, suppressing CD8+ T cell infiltration and promoting tumor growth." (PMID 39845976, 2024). "IL-6, a well-established cytokine induced by IL-1β in intestinal epithelial cells (IECs), has been shown to promote tumor progression in CAC through the activation of the oncogene STAT3 in addition to IL-11." (PMID 38607004, 2024).